EGFR (epidermal growth factor receptor)
Diseases named in the same sentence as EGFR in open-access papers (continued):
Sharing a sentence is not in itself a finding about the gene and the disease.
glioma (continued). "In the TCGA data, the expression level of EGFR in IDH wild-type glioma was elevated." (PMID 33892666, 2021). "Likewise, miR-146b, miR-124a, and miR-34a were introduced into glioma cells from transfected hBMSC-derived EVs and abrogated glioma growth by decreasing EGFR and NF-κB protein, silencing FOXA2 and downregulating MYCN, respectively." (PMID 34479611, 2021). "EGFRvIII is often co-expressed with full-length EGFR in glioma cells." (PMID 33790740, 2021). "Moreover, EGFR and c-Met co-localized in glioma cells and GBM, indicating a possible relationship between EGFR and c-Met signaling pathways." (PMID 34055785, 2021). "We are the first to demonstrate a statistical relationship between seropositivity and higher glioma grade in our cohort, which might support a mechanistic relationship between T. gondii infection and more malignant gliomas through EGFR pathway activation." (PMID 34827431, 2021). "For example, EGFR amplification has a high incidence in gliomas, which may be used as a reference index to determine the pathological grades of the tumor." (PMID 34264013, 2021). "These commonly targeted the EGFR axis (either the receptor itself or its mutants and ligands) due the relatively high prevalence of these targets in gliomas and their likely role as an oncogenic pathway in glioma." (PMID 34926242, 2021). "Since EGFR overexpression is a frequent and critical event in glioma progression and its activation leads to malignancy in many tumor types, we hypothesized that exposure to e-liquid could aggravate EGFR activation in glioma." (PMID 34495991, 2021). "Interestingly, CDKN2A and EGFR are converged on cell cycle regulation and both are altered in the early stage of glioma development." (PMID 33959491, 2021). "QSAR models have been previously utilised in the design and virtual testing of new EGFR inhibitors, which could provide future treatments for EGFR-amplified glioma." (PMID 33477674, 2021). "Tripartite motif-containing protein (TRIM) 11 promotes increased EGFR levels in glioma." (PMID 33432111, 2021). "In conclusion, AZD3759 may inhibit the progression of glioma through a synergistic blockade of the EGFR and JAK/STAT signaling pathways." (PMID 34635007, 2021). "In addition to EGFR, other tyrosine kinase receptors are usually overexpressed in pediatric high-grade gliomas, including platelet-derived growth factor receptors (PDGFRs), vascular endothelial growth factor receptor (VEGFR), among others, are targeted by CBL." (PMID 33665742, 2021). "NIR fluorescence microscopy revealed specific cellular distribution of panitumumab-IRDye800 correlated with highly proliferative tumor cells (Ki-67) and positive EGFR expression in histologically confirmed (by H&E staining) viable tumor core and infiltrative tumor margin of high-grade gliomas." (PMID 34158840, 2021). "Notch and EGFR signaling are activated in gliomas contributing to glioma stem cell maintenance." (PMID 34831271, 2021). "Moreover, FoxM1 can promote acquisition of MES features and PMT in glioma via activation of the EGFR–AKT–GSK3β signaling pathway." (PMID 34381734, 2021). "In conclusion, AZD3759 may inhibit the progression of glioma via a synergistic blockade of the EGFR and JAK/STAT signaling pathways." (PMID 34635007, 2021). "FHL2 interacts with EGFR and EGFRvIII to increase their levels and promotes glioma growth." (PMID 33987093, 2021). "This miR decreased epidermal growth factor receptor (EGFR) and NF-κB protein in 9L glioma cells in vitro, and inhibited small mothers against decapentaplegic (SMAD)-4, a protein of the SMAD family whose loss indicates poor outcome in glioma." (PMID 32349317, 2020).
glioma (continued). "Thus, lncRNA LPP-AS2 promoted glioma tumorigenesis via a miR-7-5p/EGFR/PI3K/AKT/c-MYC feedback loop." (PMID 32962742, 2020). "The NPs resulted in the downregulation of expression of EGFR protein in U87 glioma cells in vitro." (PMID 33321953, 2020). "Moreover, several endocytic/recycling molecules contribute to the stabilization of EGFR in gliomas and other cancers, increasing the robustness of the signaling cascade and/or relocating the activation of the downstream targets." (PMID 31947645, 2020). "We identified a series of vesicular transport genes that are upregulated in gliomas with alterations in EGFR, which could have a direct implication in the functionality of this receptor." (PMID 31947645, 2020). "In addition, frequently observed mutations to EGFR (27%), IDH1 (20%), PTEN (18%), and MUC16 (16%) were present in gliomas with low TOX expression (n = 158)." (PMID 32762688, 2020). "Furthermore, amplification peaks of oncogenes (PIK3C2B, PDGFRA, EGFR, CDK4), and deletion peaks of tumor suppressor genes (TUSC1, CDKN2A, CDKN2B, PTEN, FAS, BNIP3) were detected in the gliomas with a high risk score." (PMID 32023222, 2020). "The additional EGFR fusions included one ITD (TCGA-27-2523) duplicating the tyrosine kinase domain (TKD) encoded by exons 18–25, matching a previously reported TKD duplication in two glioma cell lines." (PMID 32466770, 2020). "Concomitant activation of both PI3K and EGFR signalling pathways is necessary to induce a glioma." (PMID 32878880, 2020). "This dynamic rewiring of signaling processes that is observed in glioma cells could explain our failure in the inhibition of key downstream EGFR signaling components, such as AKT and FOXO3a, after using AG1478." (PMID 32788653, 2020). "In another study, the Cetuximab (C225)-immunoliposomes (ILs) encapsulating boron anion were constructed by using novel maleimido–Polyethylene Glycol (PEG)–cholesterol for the targeted delivery of boron compounds to EGFR (+) glioma cells for boron neutron capture therapy (BNCT)." (PMID 33321953, 2020). "Multiple mutations that coactivate EGFR-Ras and PI3K/Akt pathways are required to induce a glioma." (PMID 32878880, 2020). "The aberrant glutamate release by glioma cells is primarily mediated by the xCT glutamate/cystine antiporter, whose surface expression is regulated by interaction with the epidermal growth factor receptor (EGFR)." (PMID 33187183, 2020). "Moreover, blocking of mTOR activity reinforced the sensitivity to EGFR-TKIs in glioma cells, while mTOR is also a downstream signaling molecule of PI3K-PTEN-Akt pathway." (PMID 32256584, 2020). "Likewise, monoclonal antibodies targeting EGFR (panitumumab and cetuximab) only exerted cytostatic effects on glioma cell lines." (PMID 32517694, 2020). "More importantly, EGFR can discriminate glioma cells with high sensitivity and specificity." (PMID 33198677, 2020). "Surgical resection of the glioma dramatically decreased EV EGFR levels." (PMID 33143170, 2020). "Therefore, we conclude that miR-450a-5p synergizes with gefitinib to inhibit the glioma tumorigenesis through inducing autophagy by regulating the EGFR-induced PI3K/AKT/mTOR signaling pathway, thereby enhancing the drug sensitivity of gefitinib." (PMID 32820249, 2020). "Glioma patients accepted EGFR-targeted therapy have favorable clinical outcomes." (PMID 33643898, 2020). "Thus, glioma cells with aberrant expression of EGFR have been shown preference for stiffer microenvironments, and softness of the glioma tissue positively correlated with higher tumor grade and IDH1 mutation." (PMID 33177991, 2020). "KEGG pathway analysis also showed that the neighbor genes of WNT5A were widely distributed in multiple pathways in the de novo pathways of glioma occurrence, in which crucial oncogenes (EGFR and MDM2) and 2 important tumor suppressors (PTEN and IKN4a/ARF) were closely correlated with WNT5A." (PMID 32181818, 2020).
glioma (continued). "Using this strategy, we previously reported that dynamic MRI-coupled paired-agent fluorescence tomography (MRI-PAFT) was capable of estimating the concentration of epidermal growth factor receptor (EGFR) available for binding in EGFR(+) orthotopic glioma models." (PMID 33042280, 2020). "EGFR gene amplification occurred in 19 of 60 (31.7%) gliomas." (PMID 31111685, 2020). "Blocking EGFR signaling in human carcinoma and glioma cells diminishes TF expression." (PMID 32665005, 2020). "As an alternative, we considered DYRK1A (dual-specificity tyrosine phosphorylation-regulated kinase 1A), as we have previously demonstrated that this kinase promotes the stability of EGFR in adult neural progenitors and glioma cells, where it controls the growth and the survival of the tumors." (PMID 31947645, 2020). "However, inhibition of the EGFR has been shown to protect human glioma cells from cell death under hypoxic conditions." (PMID 33092032, 2020). "More importantly, we found that c-MYC could regulate expression of LPP-AS2, suggesting that LPP-AS2 is transcriptionally regulated by c-MYC, and functions as an oncogene in glioma via an miR-7-5p/EGFR/PI3K/AKT/c-MYC feedback loop." (PMID 32962742, 2020). "Collectively, our obtained findings revealed that that miR-148a-3p delivered by glioma cells-derived exosomes could promote tumor angiogenesis by activating the EGFR/MAPK signaling pathway through inhibition of the ERRFI1 expression." (PMID 33117083, 2020). "Hence, the subsequent portion reviews the benefits of various classes of NPs used in EGFR-targeted drug delivery to manage glioma." (PMID 33321953, 2020). "In conclusion, our findings reveal a previously unknown signal relay by which SH3KBP1 mediates EGFR activation, thereby enhancing the oncogenic activity of the EGFR signaling pathway in human gliomas." (PMID 33643898, 2020). "EGFR amplification is highly related to TMZ resistance in glioma." (PMID 33195221, 2020). "However, quite valuable research study outcomes have been published that illustrated how fatty acid synthesis was related to EGFR signaling in glioma stem cells." (PMID 32328180, 2020). "In addition, miRNA-146b, which is lost in most glioma tumours, was found to reduce invasion and motility of glioma cells by silencing the EGFR." (PMID 32942702, 2020). "By combining tumor organoids of various glioma subtypes with in vivo expansion in the brain microenvironment, we present a cohort of 40 PDOX generated from primary and paired recurrent gliomas with mixed genetic backgrounds including, among others, IDH1 mutation and distinct EGFR variants." (PMID 33009951, 2020). "As a known oncogene of glioma, EGFR overexpression usually occurs as a result of copy number amplification, while in other cases where there is no copy number variation, EGFR has the ability for ligand- independent activation by some point mutations or frame-shifting insertions/deletions." (PMID 32328184, 2020). "EGFR was the top predicted co-expressed mRNA and was markedly upregulated in glioma tissues." (PMID 32962742, 2020). "Support of this proposition is provided by the promising initial findings made from a recent prospective Phase I study showing the safety and efficacy of the mannitol-induced BBB disruption procedure prior to infusion of Cetuximab in EGFR-positive glioma patients." (PMID 33003415, 2020). "Other investigations also indicate that the EGFR/mitogen-activated protein kinase (MAPK) signaling pathway may play a role in glioma." (PMID 33117083, 2020). "But, the effects of miR-450a-5p in gliomas and the roles of miR-450a-5p in the regulation of EGFR are still unknown." (PMID 32820249, 2020).
glioma (continued). "Due to epidermal growth factor receptor (EGFR) amplification, PTEN depletion and possible other mutations, overactivation of PI3K-Akt-mammalian target of rapamycin (mTOR) cascade is commonly detected in human glioma." (PMID 33159013, 2020). "Additionally, expression of EGFR was significantly increased in seven glioma cell lines (U251, SHG44, T98G, U373, U87, GOS-3, and TJ905) compared to the normal cell line HEB." (PMID 32962742, 2020). "EGFR inhibitor significantly enhances cisplatin sensitivity of human glioma cells." (PMID 33643898, 2020). "Taken together, findings obtained in the current study demonstrate that glioma cells-derived exosomal miR-148a-3p activate the EGFR/MAPK signaling pathway by repressing the expression of the ERRFI1 gene, leading to the promotion of tumor angiogenesis in glioma." (PMID 33117083, 2020). "A similar nanoparticle-mediated approach was used by Ye and co-workers, who co-delivered GOLPH3 siRNA and gefitinib (Ge, an anti-EGFR drug) in vitro (U87 and T98G glioma cell lines) and in vivo (BALB/c nude mice), obtaining growth inhibition and apoptosis induction." (PMID 32023813, 2020). "However, gliomas were refractory to TKI and EGFR-associated TKI only showed marginal benefits in recurrent malignant gliomas." (PMID 32820249, 2020). "To sum up, we found that miR-450a-5p can cooperate with gefitinib to inhibit the glioma tumorigenesis through inducing autophagy by regulating EGFR-induced PI3K/AKT/mTOR signaling pathway in glioma cells, thereby enhancing the drug sensitivity of glioma cells to gefitinib." (PMID 32820249, 2020). "Since the overexpression of EGFR has been widely found in glioma 35, 36, we investigated if EGFR in EVs could also be taken as a biomarker for glioma." (PMID 31410219, 2019). "Second, variants in CDKN2B-AS1, EGFR, and RTEL1 were associated with IDH-wildtype glioma." (PMID 31842352, 2019). "Previous studies have shown that PKM2 can act as one of the downstream transcriptional coactivators of EGF/EGFR signal transduction, which promotes disease progression in glioma cells and it might be upregulated through the EGFR-dependent NF-kB activation." (PMID 31120964, 2019). "After demonstrating the high expression of EGFR in the EVs derived from glioma cells, we examined whether EGFR in serum EVs could be used to diagnose glioma." (PMID 31410219, 2019). "Therefore, we chose U87, the glioma cell line with the lowest EGFR expression level, for in vivo testing." (PMID 31903167, 2019). "Flow cytometry analysis demonstrated that the expression level of EGFR in EVs was significantly higher in the high-grade glioma patients than in the low-grade ones (**P < 0.01, unpaired Student's t-test), suggesting a correlation between EGFR in serum EVs and tumor malignancy." (PMID 31410219, 2019). "Our findings provide foundation for further exploring whether the glioma patients with high GOLPH3 expression are more sensitive to anti‐EGFR therapy in clinic and develop possible treatment modalities for gliomas." (PMID 31094020, 2019). "Systemic administration of Dacomitinib could effectively block EGFR signal transduction in vivo and affect the growth and survival of EGFR-amplified glioma cells." (PMID 30782784, 2019). "This tracer was first evaluated in an orthotopic human EGFR-expressing glioma model in rats." (PMID 31139085, 2019). "EGFR mutation, a common alteration occurs in various tumors, is not brought to the forefront in understanding and treating glioma at present." (PMID 31801484, 2019).
glioma (continued). "Remarkably, the glioma panel allowed us to detect seven samples (31.8%) with mutations in the EGFR gene that were not previously detected using the CHP, because this panel does not cover the whole gene." (PMID 31167453, 2019). "Our study provides foundation for further exploring whether GOLPH3 high gliomas will be more sensitive to anti‐EGFR therapy in clinic and give ideas for developing new possible treatments for individual glioma patients." (PMID 31094020, 2019). "In future studies, we will develop an ensemble model that integrates multiple gene signatures designed for different subgroups of glioma patients stratified by molecular subtypes or major genomic mutations in IDH1, CIMP, EGFR and PTEN in glioma cohorts to further improve the predictive accuracy." (PMID 31097021, 2019). "Other researchers have suggested that the epidermal growth factor receptor (EGFR) expressed on the surface of exosomes may also contribute to glioma cell proliferation." (PMID 31426278, 2019). "However, studies investigating the relationship between ki-67 and EGFR in glioma patients are scarce." (PMID 31410219, 2019). "Furthermore, the lncRNAHOXA cluster antisense RNA 2 (HOXA-AS2) was overexpressed in tissues and cell lines of glioma correlating with cell viability, migration, invasion, and VM formation via negative regulation of miR-373 and EGFR over-expression." (PMID 31993365, 2019). "Indeed, IDH1 silencing in glioma cells that display co-activation of multiple RTKs (EGFR, the HGFR family member MSPR, and PDGFRs) enhances the efficacy of inhibitor combinations involving erlotinib, imatinib, and SU11274." (PMID 31010244, 2019). "Textural features, which can quantify the intra-tumor heterogeneity by evaluating the gray-level intensity and position of the pixels within an image, have also been applied to predict MGMT methylation status, EGFR expression, and immune cell infiltration status for gliomas." (PMID 30719536, 2019). "To gain further insight into the predictive value of these biomarkers in molecular subgroups of gliomas, we analyzed the effect of EGFR amplification, PTEN deletion and MGMT promoter methylation in the response to therapy using the only group with representative samples - GBM IDH-wildtype." (PMID 31623593, 2019). "However, the inhibitory effects of AZD9291 on the growth of glioma cells were nearly abolished in the cells expressing Cys797 mutant EGFR." (PMID 31122294, 2019). "We described a novel hallmark of EGFR mutation in Lower grade gliomas (WHO grade II-III), and established a connection between noted tumor-related gene phenotype, tumor immune microenvironment and clinical prognosis in LGG." (PMID 31801484, 2019). "It will be very interesting to further explore whether GOLPH3 high glioma patients will be more sensitive to anti‐EGFR therapy and provide ideas for developing new possible treatments for individual glioma patients." (PMID 31094020, 2019). "This difference may be due to higher CD19t expression levels compared to the intrinsic EGFR expression in the glioma cells, and is less likely due to differential expansion of the different CAR T cells, given their similar density in the teratomas." (PMID 31903167, 2019). "Notably, cell targets with low surface EGFR expression relative to A431 were also efficiently lysed, although production of IL-2, TNFa and IFNg was lower when glioma cell lines were used as targets compared to A431." (PMID 31903167, 2019). "However, EGFR-targeted therapies have been largely ineffective for glioma due to the rapid development of drug resistance." (PMID 31595389, 2019). "Furthermore, our results also indicate that the promotion effect of GOLPH3 on glioma proliferation is mainly through enhancing the function of EGFR related pathways." (PMID 31094020, 2019). "EGFR in EVs highly correlates with the malignancy of glioma." (PMID 31410219, 2019).